INS (insulin)
Diseases named in the same sentence as INS in open-access papers (continued):
Sharing a sentence is not in itself a finding about the gene and the disease.
bacterial infection (continued). "Current survival results demonstrate that suppression of insulin signaling in D. melanogaster by mutation of the insulin receptor substrate Chico does not affect the survival of the mutant flies upon bacterial infection." (PMID 27134635, 2016). "It has been demonstrated that bacterial infection may reduce or increase the secretion of insulin based on the type of micro-organisms which penetrate the pancreatic tissue." (PMID 27631977, 2016). "Collectively, these findings suggest that sterile inflammation or bacterial infections, by increasing peripheral insulin resistance and/or placental nutrient transport, may contribute to the increased fat deposition observed in infants of women with GDM." (PMID 25541965, 2014). "daf-2 insulin/IGF-1 signaling (IIS) mutants are long-lived and exhibit increased resistance to bacterial infection." (PMID 40909712, 2025). "Molecular signals, including insulin and p38 MAPK have been identified as playing crucial roles in the regulation of bacterial infection." (PMID 38529191, 2024). "Significantly, the DAF-16/FOXO transcription factor, a key component of the insulin/IGF-1 signaling pathway, has been identified as a crucial immune regulator in the defense against bacterial infections." (PMID 39728497, 2024). "Some molecular signals including insulin, Wnt, ELT-2, TGF-β, p38 MAPK, and PCD related signals have been identified to be involved in regulating the bacterial infection." (PMID 37050896, 2023). "Insulin, p38 MAPK, Wnt, DBL-1/TGF-β, ELT-2, and PCD are important signals required for the control of innate immunity against bacterial infection in nematodes." (PMID 36120363, 2022). "Meanwhile, bacterial infection (DN315) decreased the secretion of CINC-2 by approximately 92%, whereas insulin treatment of infected diabetic animals increased the PeLF CINC-2 by 20.3-fold (DN315+i1) and 10-fold (DN315+i2)." (PMID 30705678, 2018). "DIGE analysis of the nematode proteome induced by S. flexneri suggests that both the DAF-2/DAF-16 insulin signaling pathway and the p38 MAPK pathway are induced in response to bacterial infection." (PMID 25187942, 2014). "Given that the insulin/IGF-1 signaling pathway and the p38 MAPK pathway in C. elegans are required for the defense response against several bacterial infections in intestine, we examined the role of these pathways against P. luminescens." (PMID 25279274, 2014). "Such genes may affect resistance to bacterial infection and may or may not be subject to regulation by insulin signaling and/or hormones such as JH and 20E." (PMID 37524824, 2023). "Likewise, insulin/insulin-like growth factor (IGF) signaling, through the insulin/IGF-1 transmembrane receptor homolog DAF-2, integrates nutritional cues and fat utilization to enable survival during bacterial infection." (PMID 37906605, 2023).
genetic disorder (32 papers, 2011 to 2025). "WRS is a rare genetic disorder that is defined by neonatal/early-onset diabetes mellitus that requires insulin; it is typically associated with skeletal dysplasia and developmental deficiencies." (PMID 34549728, 2021). "CHI is a genetic disorder caused by mutations in the regulation of the potassium channel which is closely involved in insulin secretion by the pancreatic β cell." (PMID 32537058, 2020). "This channel regulates insulin secretion in response to glucose challenge, and is involved in genetic diseases associated with insulin/glucose dismetabolism." (PMID 27242528, 2016). "Congenital hyperinsulinism (HI) is a rare genetic disease, occurring in roughly 1/25,000–1/50,000 infants, that is characterized by overproduction of insulin by pancreatic beta cells, leading to persistent hypoglycemia." (PMID 40894704, 2025). "Congenital hyperinsulinism (HI) is a rare genetic disease characterized by overproduction of insulin." (PMID 40894704, 2025). "Our findings indicate that approximately 1 in 40 hospitalised patients had RED-related codes, with rare disorders of calcium and phosphate homeostasis being the most common subtype, followed by genetic disorders of glucose and insulin homeostasis." (PMID 39651662, 2024). "These include inherited adrenal, pituitary, and thyroid dysfunctions, genetic disorders related to glucose and insulin homeostasis, rare anomalies in phosphocalcic metabolism, disorders impacting sexual development and maturation, and others." (PMID 39651662, 2024). "Congenital hyperinsulinism (CHI) is a group of genetic disorders characterized by the impaired regulation of insulin production in response to blood glucose (BG) levels, resulting in excess insulin." (PMID 36202918, 2022). "MTG6, pituitary, (20%) and MTG1, adrenal (19%) were slightly overrepresented among the individual responses, followed by MTG3, Genetic disorders of glucose and insulin homeostasis and MTG7, Sex Development and Maturation (12% each)." (PMID 33289690, 2021). "Most responses were received from patients of the Adrenal (39%), Pituitary (29%) and Thyroid (13%) MTGs, whereas the Genetic disorders of glucose and insulin homoeostasis MTG had the lowest representation (2%)." (PMID 33534110, 2021). "Congenital hyperinsulinism (CHI) refers to a group of rare genetic disorders that are characterized by excess insulin secretion by pancreatic β-cells." (PMID 28600547, 2017). "However, corticosteroids or growth hormone therapy and genetic diseases may affect insulin sensitivity lifelong." (PMID 31214120, 2019).
myopathy (27 papers, 2009 to 2025). A disease of the muscle in which the muscle fibers do not function properly. "In skeletal muscle, fat infiltration is a common feature in several myopathies and is associated with muscular dysfunction and insulin resistance." (PMID 33244879, 2021). "In T1DM, the deficiency of insulin and/or C-peptide as potential survival factors may play a role in the pathogenesis of myopathy by rendering skeletal muscle more susceptible to the toxic effects of insults such as simvastatin." (PMID 30987105, 2019). "Impaired insulin signaling particularly the failure of GLUT-4 translocation reduces protein synthesis and is implicated in critical myopathy." (PMID 40601169, 2025). "The decrease in insulin/IGF1 signaling leads to myopathy through downregulation of the Kit ligand and the ERK signaling pathways." (PMID 37759758, 2023). "In skeletal muscle, IMAT is a common feature in several myopathies and is related to muscular dysfunction and insulin resistance." (PMID 35915136, 2022). "The properties of myopathy include insulin resistance, muscle weakness and atrophy, oxidative stress, and mitochondrial dysfunction." (PMID 34066110, 2021). "The results suggest that chronic alcohol-induced myopathy is mediated by broad impairments of insulin/IGF signaling through Akt, as well as increased oxidative stress." (PMID 23016132, 2012). "While mitochondria play an important role in intracellular glucose and lactate metabolism in insulin-sensitive tissues such as muscles, appropriate strategies for glycemic control have not yet been established in a patient with mitochondrial disease, which is often complicated by myopathy." (PMID 37139126, 2023). "Although these mice develop an early onset severe myopathy, we believed that because this line expresses high levels of TDP-43 in skeletal muscle, it would manifest similar abnormalities in Glut4 translocation in response to insulin." (PMID 23967244, 2013). "In addition, the studies herein suggest that increased oxidative stress, which itself promotes insulin/IGF resistance, contributes to the pathogenesis of chronic ethanol induced myopathy." (PMID 23016132, 2012). "At the mRNA level, the essential insulin-dependent metabolic gene AKT2 and the down-regulated genes, namely FOXO3, were significantly upregulated in muscle parts with critical myopathy and without critical myopathy, compared to controls." (PMID 36904071, 2023). "Insulin-dependent genes critical for the insulin signalling pathway upstream of AKT2, such as IGF1 receptor, IRS1, and PI3Kp110a, were markedly down-regulated in patients with or without acutely understrength myopathy compared to controls." (PMID 36904071, 2023).
infectious disease (26 papers, 2014 to 2025). A disorder directly resulting from the presence and activity of a microbial, viral, or parasitic agent in humans. "The KEGG protein interaction network showed multiple species signaling pathways are associated with bacterial infectious diseases: circadian entrainment, insulin secretion, the Wnt signaling pathway, the thyroid hormone signaling pathway, and the Hippo signaling pathway." (PMID 38200892, 2024). "This prevalent poor knowledge is probably because, health care professionals who are supposed to put clients through on the technicalities involved in modification and regulation of insulin dose according to diet, exercise and infectious diseases are also deficient themselves." (PMID 24397956, 2014). "Gender differences were reflected in adverse respiratory illness, cardiovascular system, insulin secretion, and infectious diseases from embryonic to infant stages." (PMID 37828431, 2023). "Professional health care providers are partly to blame for participants being in the dark as to adjusting their insulin dose in relation to diet and infectious diseases." (PMID 24397956, 2014). "The current study findings offer further assurance that DPP-4 inhibitors are safe to be used together with insulin in progressed T2DM patients in terms of infectious disease risks, whereas the link between SGLT-2 inhibitors and genital infection risks was also confirmed in our study." (PMID 37891260, 2023). "We hypothesize that treating adipocyte dysfunction with new insulin sensitizers might significantly impact the interface of infectious disease and chronic metabolic disease." (PMID 34863942, 2022). "Early in the preclinical phase of AD, the shared biological pathways between MCI and T2D are mostly related to inflammation and infectious diseases, whereas later as the disease progresses, in AD–T2D, the insulin signaling becomes dysregulated and the cardiovascular system gets compromised." (PMID 31849586, 2019). "Furthermore, majority did not know how to modify their insulin dosage in relation to diet and infectious diseases such as flu." (PMID 24397956, 2014).
brain disorder (22 papers, 2012 to 2025). A disease affecting the brain or part of the brain. "An established feature of alcohol-related brain disease, both in humans and experimental animal models, is brain insulin/IGF resistance accompanied by neuronal loss, white matter atrophy, and reduced myelin gene expression." (PMID 23016131, 2012). "In this review, we have summarized the key roles of insulin and insulin receptors in healthy brains and in different brain disorders." (PMID 39518747, 2024). "This review showed therapeutic approaches like medications, exercise, intermittent fasting to brain disorders centered around insulin signaling and metabolism, as well as insulin resistance." (PMID 39518747, 2024). "Various novel treatments addressing the pathogenic mechanisms of HIV-induced brain disease are currently under investigation, including PPAR-gamma agonists, PD1 inhibition, curcumin, intranasal insulin, and Jak inhibitors." (PMID 37762667, 2023). "Other properties include antiallergic, antimicrobial, immunostimulatory, and anti-inflammatory effects, as well as increased insulin activity and protection against cardiovascular and brain disease." (PMID 37371967, 2023). "There are two main QBS tests able to verify if the IRR of brain disorders is related to AD: the test of insulin secretion acute peak and the test of microcirculatory activation of the brain." (PMID 23520438, 2013). "Awareness of the contributions of impaired insulin/IGF-1 signaling in alcohol-related brain diseases led to the concept that the deleterious effects of ethanol could be minimized or prevented by therapeutic targeting with insulin sensitizer agents." (PMID 37108779, 2023). "Finally, more studies are necessary to elucidate the benefits of melatonin treatments under brain disorders related to impairments in glucose and insulin homeostasis." (PMID 36902233, 2023). "Therefore, although the benefits of melatonin for DM are still controversial, the interplay between melatonin and neurogenesis is promising as a potential treatment for brain disorders related to impairments in glucose and insulin homeostasis." (PMID 36902233, 2023). "An interesting instance is the causative roleof defective insulin signaling pathway in several brain disorder which could be corrected by insulin treatment." (PMID 31213068, 2019). "Therefore; dysfunction at different levels of insulin signalling and metabolism can contribute to the development of a number of brain disorders." (PMID 30355995, 2018). "Therefore, alterations in insulin metabolism and signalling in the Central Nervous System (CNS) can contribute to the development of many brain disorders." (PMID 30355995, 2018). "In diabetic rats, CIN has been reported to increase glucose uptake and improve insulin sensitivity in adipose and muscle, increase glycogen synthesis in the liver, restore pancreatic cell function, delay gastric emptying and improve diabetic renal and brain disorders through multiple methods." (PMID 39861427, 2025). "In summary, the exploration of insulin RMT offers promising avenues for the development of antibody-based delivery platforms, potentially revolutionizing therapeutic interventions for brain disorders." (PMID 39204177, 2024). "Clark IA, Vissel B. Inflammation-sleep interface in brain disease: TNF, insulin, orexin." (PMID 34161418, 2021).
gastrointestinal disorders (16 papers, 2016 to 2025). "RFX6 is typically expressed in the pancreas and gastrointestinal tract, essential for pancreatic development and insulin production, with its dysregulation implicated in gastrointestinal disorders." (PMID 38932472, 2024). "Fiber intake is important for health, especially for gastrointestinal health and function, as well as for improved insulin sensitivity and weight regulation, while low-fiber diets are associated with various metabolic and gastrointestinal disorders." (PMID 39458449, 2024). "The study endpoint was the effect on plasma glucose, insulin, C-peptide concentrations and gastrointestinal disorders." (PMID 38914694, 2024). "When used as add-on therapy to metformin, liraglutide significantly increased the risk of gastrointestinal disorders (RR = 1.59, 95%CI: 1.15, 2.19; P = 0.005) compared with control (placebo, dulaglutide, sitagliptin, glimepiride, NPH, and insulin glargine)." (PMID 27600499, 2016).
neurodevelopmental disorder (11 papers, 2017 to 2025). A behavioral and cognitive disorder with onset during the developmental period that involves impaired or aberrant development of intellectual, motor, or social functions. "Multiple factors can contribute to insulin signaling dysfunction in neurodevelopmental disorders such as ASD, including inflammation, oxidative stress, and mitochondrial dysfunction, all of which can lead to IR." (PMID 40650313, 2025). "All of these results are consistent with a role for insulin-signaling in the circadian and cognitive effects of this neurodevelopmental disorder." (PMID 28430154, 2017). "Insulin regulates placental function, and impairment in the signalling pathway in the placenta has been shown to particularly affect the development of male offspring in ways that are common to neurodevelopmental disorders." (PMID 40613865, 2025). "The hypothesis of the present study is that insulin, when administered directly to the brain, can be used as a therapeutic approach in neurodevelopmental disorders such as ASD." (PMID 39329976, 2024). "These hypotheses could be assessed in pregnant animal models exhibiting insulin signaling dysfunction to evaluate whether maternal gut dysbiosis promotes the migration of maternal bacterial antigens into the fetal neuronal tissue, potentially triggering neurodevelopmental disorders such as ASD." (PMID 40650313, 2025). "In patients with neurodevelopmental disorders such as ASD, the production of insulin in neurons may be more limited compared to that in neurotypical individuals." (PMID 39329976, 2024).
mitochondrial disease (9 papers, 2015 to 2025). "Inhibition of insulin/IGF‐1 signaling (IIS) represents a promising avenue for the treatment of mitochondrial diseases, although many of the molecular mechanisms underlying this beneficial effect remain elusive." (PMID 30796049, 2019). "Intravenous insulin infusion therapy in patients with mitochondrial disease may unmask derangements of intracellular glucose metabolism in response to insulin signaling." (PMID 37139126, 2023). "Evidently, perturbation of insulin/IGF-1 receptor signaling contributes to tissue damage in mitochondrial disease, which may allow therapeutic intervention against a wide spectrum of diseases." (PMID 25643582, 2015). "It is also possible that S6K1 disruption is inducing changes in the signaling network through its regulation of the insulin/IGF-1 signaling network or additional targets, or that S6K1 disruption is alleviating mitochondrial disease in these animals by a mechanism distinct from rapamycin." (PMID 28919908, 2017).
respiratory disease (9 papers, 2013 to 2025). "Studies have shown associations between medications such as metformin, pioglitazone, and insulin and respiratory system diseases, but the conclusions vary." (PMID 39091286, 2024).
gastrointestinal disease (8 papers, 2015 to 2025). A disease that occurs in the gastrointestinal system, excluding the hepatobiliary system. "However, our research found no causal evidence for the impact of metformin, GLP-1 agonists, SGLT2 inhibitors, DPP 4 inhibitors, insulin and its analogs, thiazolidinediones, or alpha-glucosidase inhibitors on gastrointestinal diseases." (PMID 38918852, 2024). "Our study investigated the causal relationship of seven common antidiabetic drug targets–metformin, GLP-1 receptor agonists, SGLT2 inhibitors, DPP-4 inhibitors, insulin and its analogs, thiazolidinediones, sulfonylureas and alpha-glucosidase inhibitors–on various gastrointestinal diseases." (PMID 38918852, 2024). "Fasting insulin mediated the 6.79%–38.63% effect of MVPA on 8 gastrointestinal diseases." (PMID 38583262, 2024). "Here, Perley and Kipnis showed that the incretin part of the insulin response to oral glucose in man constituted more than half, later confirmed to be probably two thirds or more of the insulin response in healthy people, though smaller, with high age and some gastrointestinal diseases." (PMID 30061863, 2018). "Our MR results showed that SGLT2 inhibitors, DDP-4 inhibitors, Insulin and its analogs, Thiazolidinedione, and other drugs did not have significant effects on gastrointestinal diseases and were not further analyzed." (PMID 38918852, 2024).